BRCA2 (BRCA2 DNA repair associated)
Diseases named in the same sentence as BRCA2 in open-access papers (continued):
Sharing a sentence is not in itself a finding about the gene and the disease.
pancreatic ductal adenocarcinoma (18 papers, 2015 to 2025). An infiltrating adenocarcinoma that arises from the epithelial cells of the pancreas. "A 61-year-old female patient harboring germline BRCA2 mutation was treated at our institution for a pancreatic ductal adenocarcinoma with lung and liver metastases." (PMID 35200549, 2022). "Recently, inherited mutations in correlation with PDAC have gained focused attention, and a pathogenic BRCA1 and BRCA2 mutation was identified in a large cohort in 4.6% among pancreatic ductal adenocarcinoma patients." (PMID 28978057, 2017). "For example, a study involving 854 patients with pancreatic ductal adenocarcinoma showed that 12 patients (1.4 %) had BRCA2 and 3 patients (0.35 %) had BRCA1 deleterious germline mutations." (PMID 33563323, 2021). "Multiple genes that are associated with well-known hereditary cancer syndromes such as BRCA1 and BRCA2, PALB2, CDKN2A, ATM and the DNA mismatch repair genes were found to be associated with pancreatic ductal adenocarcinoma as well." (PMID 28978057, 2017). "An IF and IHC panel for BRCA1 and BRCA2 expression was performed on normal pancreas, pancreatic ductal adenocarcinoma (PDAC), and the PACC PDTX model." (PMID 27165126, 2016). "We also noted that ART558 sensitivity was not limited to genetically engineered DLD1.BRCA2‒/‒ cells and was also apparent in tumour cells with a naturally-occurring pathogenic BRCA2 mutation, namely CAPAN1 pancreatic ductal adenocarcinoma tumour cells (BRCA2 c.6174delT25, CAPAN1Parental)." (PMID 34140467, 2021). "For this purpose, we used conditional null alleles of Palb2 (Palb2flox2-3), Brca1 (Brca1flox2) and Brca2 (Brca2flox3-4) in combination with the well characterized Pdx1-Cre transgene that has been extensively used for modeling pancreatic ductal adenocarcinoma (PDAC) in mice." (PMID 31877165, 2019).
Familial adenomatous polyposis (17 papers, 2012 to 2025). Familial adenomatous polyposis (FAP) is characterized by the development of hundreds to thousands of adenomas in the rectum and colon during the second decade of life. "As expected, MUTYH associated with recessive familial adenomatous polyposis, the only two homozygotes of which also carry biallelic MUTYH variants, had the highest allele frequency, followed by VHL, BRCA1, BRCA2, and PALB2." (PMID 39301547, 2024). "For example, MRI was a dominant strategy for individuals in the former group, which included those with FPC with 1–2 FDRs, hereditary non-polypoid colorectal cancer syndrome, familial adenomatous polyposis, and BRCA2 mutations." (PMID 40277782, 2025). "These cases include individuals with FPC with one or two FDRs with PC, hereditary non-polypoid colorectal cancer syndrome, familial adenomatous polyposis, and BRCA2 mutations." (PMID 40277782, 2025). "In addition, the development of IPMNs has been related to genetic syndromes, such as familial adenomatous polyposis (FAP), BRCA2-associated hereditary breast cancer, Peutz–Jeghers syndrome, Von Hippel–Lindau (VHL) syndrome, familial pancreatic cancer (FPC), and various autoimmune diseases." (PMID 37575378, 2023).
stomach cancer (17 papers, 2002 to 2024). "In particular, Brca2 deficiency promotes gastric tumor formation when genome stability is selectively impaired in gastric epithelial cells." (PMID 32980867, 2020). "In the case of the CRC and the stomach carcinoma, the hypermutation detected was due to the presence of microsatellite instability (MSI) (MMR deficiency signatures’ contribution: 77%), and to the presence of BRCA2 p.Pro1088Leufs*16 (BRCA1/2 signature contribution: 52%), respectively." (PMID 32792570, 2020). "In addition, gastric tumor cells exhibited evident DNA damage and DNA repair defect, supported by downregulation of well-known genes involved in DNA damage and repair response, including RAD51, BRAC1, BRCA2 and BARD1." (PMID 36755269, 2023). "Notably, BRCA2 mutations were also associated with HRD in urothelial, squamous cell lung, and stomach carcinomas, where tumor response to PARPi has not yet been associated with HR mutations or HRD." (PMID 34572800, 2021).
anemia (16 papers, 2008 to 2025). A reduction in the number of red blood cells, the amount of hemoglobin, and/or the volume of packed red blood cells. "Mammalian RAD51, in collaboration with BRCA1, BRCA2, and Fanconi anemia proteins, plays a critical role in preventing nascent DNA degradation by MRE11." (PMID 40737093, 2025). "For the 33 patients in the olaparib arm identified with a somatic BRCA1 or BRCA2 alteration, 18% had grade ≥3 anaemia." (PMID 35598359, 2022). "BRCA2, Fanconi anemia complementation group protein C (FANCC) and a combination of FANCC and Fanconi anemia complementation group protein G (FANCG) mutations have been found in pancreatic cancer patients." (PMID 28471392, 2017). "Additionally, among 42 patients in the olaparib arm identified with either a germline BRCA1 or BRCA2 alteration, 26% of these patients had grade ≥3 anaemia." (PMID 35598359, 2022). "The Fanconi anaemia proteins together with BRCA1/FANCS and BRCA2/FANCD1 act in a common pathway, FANCA/BRCA pathway, to coordinate the cellular response to DNA damage, driving DNA repair through homologous recombination (HR)." (PMID 36622663, 2023). "Many proteins participate in this protection including BRCA2, RAD51, WRNIP1, or Fanconi anemia proteins (37, 40, 43, –, 45)." (PMID 31757807, 2020).
Peutz-Jeghers syndrome (16 papers, 2009 to 2026). An autosomal dominant disorder caused by pathogenic variants in the STK11 gene, characterized by hamartomatous polyps in the gastrointestinal tract, mucocutaneous pigmentation and increased risk of GI and extra-GI malignancies. "Seventy-nine participants met the FPC criteria (≥ two first-degree relatives affected), 22 individuals had both a BRCA2 pathogenic variant and a close relative with PC and one had a clinical diagnosis of Peutz-Jeghers syndrome." (PMID 31666883, 2019). "This includes pathogenic variants in cancer predisposition genes, e.g. BRCA2 and PALB2; Lynch Syndrome, Peutz-Jeghers Syndrome (PJS), Familial Atypical Multiple Mole Melanoma and Hereditary Pancreatitis." (PMID 31666883, 2019). "Current CAPS guidelines recommend screening those with at least two affected FDRs; patients with Peutz-Jeghers syndrome (PJS); and P16, BRCA2 and hereditary non-polyposis colorectal cancer (HNPCC) mutation carriers with ≥1 affected FDR." (PMID 32601617, 2019).
Wilms tumor (16 papers, 2012 to 2025). An embryonal neoplasm characterized by the presence of epithelial, mesenchymal, and blastema components. "FA-D1 patients with biallelic mutation in BRCA2 develop cancers such as myeloid and lymphatic malignancies, medulloblastoma and Wilms tumor in early childhood, typically in as high as 90% of patients by 7 years of age." (PMID 34356050, 2021). "Two of the 59 patients (3%) with Wilms’ tumor carried pathogenic variants in BRCA2 and SDHA." (PMID 33674644, 2021). "Given that embryonal tumors in patients with biallelic pathogenic variants of BRCA2 include neuroblastoma and Wilms tumors, it is tempting to speculate that the essential function of BRCA2 in prevention of these two blue cell tumors will also include BRCA2 function at G4-quadruplexes." (PMID 40854122, 2025). "Of note, such efforts have documented cases of Wilms tumour with pathogenic germline mutations in genes conferring increased risk to adult epithelial cancers, such as CHEK2 or BRCA2." (PMID 39665570, 2025). "Meanwhile, as one of the FA DNA repair-related genes, some specific BRCA2 mutants lead to a severe subset FA accompanying the early onset of cancer, including acute myeloid leukemia, brain tumors, Wilms tumor, and so on." (PMID 34367235, 2021). "A further five constitutionally mutated genes—PIK3CA, FBXW7, ASXL1, BRCA2, and CDC73—were somatically mutated in other cancer types but have not been proven to be somatic drivers in Wilms tumour." (PMID 30885698, 2019). "VUS were also detected in NF1 in a patient without clinical symptoms of NF1, BRCA2 in a patient with nephroblastoma, SMARCA4 in a patient with Ewing sarcoma, and SEC23B, a candidate gene for Cowden, in a patient with multiple tumours and an additional pathogenic heterozygous RECQL4 variant." (PMID 37507557, 2023).
brain tumors (15 papers, 2012 to 2026). "Pathogenic GVs in BRCA2 were detected in tumor families and brain tumor families." (PMID 41546701, 2026). "Similar to our findings, BRCA2 variants have been linked to pediatric brain tumors." (PMID 41546701, 2026). "In a meta-analysis, heterozygous ClinVar LP/P BRCA2 GVs were significantly more frequent in 876 children and adolescents with brain tumors than in a control cohort." (PMID 41546701, 2026). "In BRCA2 GV carriers and their families, tumors of the brain (6/17, 35%), breast (4/17, 24%), skin (3/17, 18%), lung (2/17, 12%), bladder, and colon (1/17, 6% each) were observed." (PMID 41546701, 2026). "This evidence from tissue-specific knockout of HR factors reinforces the idea that different modes of tumor initiation depend on which step of HR is affected and suggests a special BRCA2 function in the inhibition of brain tumor development." (PMID 33923105, 2021). "It has been shown that >80% junctions of SVs in Brca2 mutant murine brain tumors have no or very short microhomologies (0–1 bp), suggesting that cNHEJ are mainly responsible for the ligation." (PMID 32139898, 2020). "The Slovene family which has monoallelic BRCA2 c.658_659delGT does not, however, exhibit any brain tumors and is affected mostly by quite late onset of OC." (PMID 22923021, 2012).
gynecological cancer (15 papers, 2018 to 2026). "BRCA2 plays a pivotal role in DNA repair and tumor suppression, with its dysregulation linked to breast and gynecological cancers." (PMID 40640493, 2025). "BRCA2 mutation c.2307delT p.I770Ffs*2 was the hotspot firstly reported here among Chinese patients with gynecological cancer." (PMID 37064128, 2023). "A new mutation hotspot in BRCA2 (I770) was firstly discovered among Chinese patients with gynecological cancer." (PMID 37064128, 2023). "Due to the pronounced role of BRCA1 and BRCA2 in hereditary breast and ovarian cancer, different mutations and variants of BARD1 were first investigated in breast cancers and various gynecological cancers in the late 1990s and early 2000s." (PMID 32708251, 2020). "Women with BC or gynecological cancer who had tested negative for path_BRCA1 or path_BRCA2 variants were included." (PMID 29371908, 2018). "Among prospectively detected BC or gynecological cancer phenocopies in the path_BRCA1/2 families, we found that 4/48 have pathogenic variants in high-penetrance cancer genes: two BC- and one CRC-associated gene (ATM, BRCA2 and MSH6, respectively)." (PMID 29371908, 2018). "We will then describe different variations of BARD1 present in non-breast and non-gynecological cancers, which are not driven by mutations in either BRCA1 or BRCA2 genes." (PMID 32708251, 2020). "Together with the observation that low DPP9 expression was associated with poor survival in UCEC, it might suggest that DPP9 is a suppressor of gynecological cancer, which would align with the recently discovered role of DPP9 in BRCA2 homeostasis and DNA repair." (PMID 33915844, 2021).
hereditary ovarian cancer (15 papers, 2009 to 2023). "BRCA2 is another important tumor suppressor gene that is also associated with hereditary ovarian cancer." (PMID 37110218, 2023). "Although mutations on BRCA2 is one of the major cause of hereditary ovarian cancers, the expression profiles are also altered in sporadic ovarian cancers, which are known as the “BRCAness”of sporadic cancers." (PMID 26496279, 2015). "While germline mutations in BRCA1 and BRCA2 predispose to hereditary ovarian carcinoma, somatic mutations in these genes are rare in sporadic ovarian carcinomas." (PMID 19602291, 2009). "Hereditary ovarian cancer comprises 10 to 15% of all cases of ovarian malignancies and is mainly associated with germline mutations in the BRCA1 and BRCA2 genes." (PMID 23344037, 2013). "Restoration of BRCA1 and BRCA2 mediates resistance to platinum chemotherapy in recurrent BRCA1 and BRCA2 mutated hereditary ovarian carcinomas." (PMID 19602291, 2009). "The BRCA1 and BRCA2 gene status undisputedly plays a key role in genome integrity and hereditary ovarian cancer pathogenesis; however, the frequency and precise prognostic role of BRCA mutations at different locations of the genes remains largely unknown." (PMID 34898566, 2021).
lymphoma (15 papers, 2007 to 2025). A malignant (clonal) proliferation of B- lymphocytes or T- lymphocytes which involves the lymph nodes, bone marrow and/or extranodal sites. "Survivors of pediatric or adolescent lymphomas (N = 1380) were enriched for BRCA2 mutations compared to gnomAD." (PMID 40253392, 2025). "Two women carrying recurrent mutations in BRCA2 (c.1763_1766delATAA, p.Asn588Serfs*25) and ATM (c.5496 + 2_5496 + 5delTAAG) genes had the diagnosis of other types of cancer that is, lymphoma and, thyroid and gastric, respectively." (PMID 38890714, 2024). "Conversely, a few studies have suggested that the BRCA genes are associated with increased risk of NHL, HL, or MM including BRCA1 (7.7-fold increase) and BRCA2 (5.9-fold increase) in the Japanese population and BRCA2 (3.3-fold increase) in pediatric or adolescent lymphoma survivors from St." (PMID 40253392, 2025). "One woman was diagnosed with lymphoma with a prior ductal BC, and she had a heterozygous BRCA2 c.1763_1766delATAA, p.Asn588Serfs*25; the other one had three cancers, thyroid, gastric, and ductal BC harboring an ATM c.5496 + 2_5496 + 5delTAAG, a likely pathogenic mutation." (PMID 38890714, 2024). "Moreover, the risks for lymphoma (RR = 3.16, 95% CI = 1.13-8.83; P = 0.046) and kidney cancer (RR = 4.07, 95% CI = 1.22-13.56; P = 0.046) in female relatives of BRCA2 carriers were significantly higher than female relatives of non-carriers." (PMID 36861435, 2023).
hereditary non-polyposis colorectal cancer (14 papers, 1998 to 2025). "Our models are not intended to predict the probability of the three cancers among women known to be at much higher than average risk, e.g., women with a mutation in BRCA1 or BRCA2 or with hereditary non-polyposis colorectal cancer (HNPCC)." (PMID 23935463, 2013). "Recent literature reports state that the screening is only recommended for the high-risk population identified as those with a family history of the disease, women with BRCA1 and BRCA2 mutations, or with hereditary nonpolyposis colorectal cancer." (PMID 21577260, 2011).
lymph node metastasis (14 papers, 2015 to 2024). "On the other hand, there were statistically significant negative correlations between perineural invasion and phosphotidylinositol-4,5-biphosphate 3-kinase (PIK3CA) mutation (P = .043) and between lymph node metastasis and BRCA2 mutation (P = .009)." (PMID 37737217, 2023). "We found that most of the mutations carried by patients with an onset age of ≤ 45 years were located in the region of exon 15 or behind exon 15, and 80.0% of the patients with BRCA2 possible disease-causing mutations had lymph node metastases." (PMID 34570441, 2021). "Tumor diameter, lymph node metastasis and skin viscosity were the risk factors affecting the expression level of BRCA2, and tumor differentiation was the protective factor." (PMID 31700821, 2019). "Further multivariate analysis showed that tumor diameter, lymph node metastasis and skin viscosity were the risk factors affecting the expression level of BRCA2, and tumor differentiation was the protective factor." (PMID 31700821, 2019). "MRP3 expression did not vary significantly with age (P>0.9999) but showed significant differences with menopausal status, tumor size, histology, clinical stage, lymph node metastasis, PR status, and BRCA2 status." (PMID 39267845, 2024). "There were significant differences in the expression of BRCA2 with tumor diameter, lymph node metastasis, skin viscosity and tumor differentiation degree (P<0.001)." (PMID 31700821, 2019). "For ER+ cancer, lymph node metastases were present in 60.9%, 54.8%, and 42.5% of BRCA2-carriers, young and older patients, respectively, whereas for ER-negative cancer the proportion with lymph node involvement was lowest in BRCA2-carriers and highest in young patients." (PMID 38036573, 2023). "In contrast to a previous report showing that axillary node involvement was more frequent in BRCA2 carriers, in our study BRCA2 mutations were more frequently found in patients without lymph node metastasis." (PMID 35494038, 2022). "The BRCA2 p.Ser1404Term mutation carriers were more than 45 years of age, were in stage I, and had no lymph node metastasis." (PMID 34570441, 2021). "In addition, a panel with BRCA1 mutation, BRCA2 mutation, and five serum markers (AFP, CA125, CA19‐9, CA242 and HE4) showed a good performance for identifying patients with lymph node metastasis (AUC = 0.843, Sensitivity = 0.600, Specificity = 0.902)." (PMID 30972954, 2019). "We believe that the results of our study on BRCA2, the relationship of which with lymph node metastasis has not been agreed upon and the association with clinicopathologic parameters has not yet been sufficiently investigated, will make a significant contribution to the literature." (PMID 37737217, 2023). "In addition, more patients with lymph node metastasis were found in BRCA2 and other CPGs subgroups than the non-GPVs group (60.7% in BRCA2 mutation-carriers and 50.7% in other CPGs mutation-carriers vs. 38.2% in non-carriers, p=1.7×10-6 and 0.04, respectively)." (PMID 34336698, 2021). "BRCA2 carriers were more likely to have positive regional lymph node metastasis than non-carriers (p = 0.012)." (PMID 34206661, 2021). "Significant relationships determined between KRAS exon 2 and mucinous morphology, PIK3CA and absence of perineural invasion, BRAF and tumor differentiation and localization, MSH3 and tumor diameter, and BRCA2 and absence of lymph node metastasis were findings that have contributed to the literature." (PMID 37737217, 2023).